FGF21 (fibroblast growth factor 21)
Diseases named in the same sentence as FGF21 in open-access papers (continued):
Sharing a sentence is not in itself a finding about the gene and the disease.
Insulin resistance (continued). "FGF21 analog is currently in the clinical trial stage and has been shown to increase adiponectin, a favorable adipokine, and to ameliorate insulin resistance in humans." (PMID 40747315, 2025). "Since FGF-21 levels are correlated with adipose tissue mass, plasma glucose and insulin levels (insulin resistance)." (PMID 41341131, 2025). "In this review, we describe the physiological properties and signaling pathways of FGF21 and elaborate on the mechanism of action of FGF21 in improving insulin resistance." (PMID 40881124, 2025). "In conclusion, FGF21 demonstrates an irreplaceable role in insulin resistance, both by increasing insulin signaling to enhance glucose uptake and by increasing lipocalin secretion to elevate insulin sensitivity." (PMID 40881124, 2025). "Our findings corroborate these observations, revealing increased circulating FGF-21 levels in individuals with metabolic syndrome, insulin resistance, and dyslipidemia." (PMID 40559404, 2025). "It has been shown that FGF21 improves insulin sensitivity, insulin resistance and β-cell function, and exerts a protective effect through alleviating ROS-mediated oxidative stress, inflammation and apoptosis." (PMID 39819596, 2025). "The attenuation of systemic insulin resistance attributed to the PTEN-dependent FGF21 upregulation was also confirmed by deleting FGF21 alongside ChREBP to check the metabolic alterations in DIO mice." (PMID 40311678, 2025). "FGF21 also improves insulin resistance by acting directly on islet β-cells by increasing the number of insulin receptors, inhibiting glucolipotoxicity-induced apoptosis, increasing insulin secretion, and reducing α-cell glucagon secretion." (PMID 39409124, 2024). "Thiazolidinediones increase the transcriptional activity of PPAR-γ by increasing the expression of fibroblast growth factor 21 (FGF21), thereby improving insulin resistance in diabetic patients." (PMID 38884020, 2024). "FGF-21 plays a role in metabolic states like insulin resistance, lipid accumulation, and gluconeogenesis." (PMID 39335666, 2024). "As evidence shown, FGF21 is reported to prevent fatty liver formation and insulin resistance in obese mice model and numerous studies showed FGF21 analogue reduced fat mass and alleviated hyperglycaemia, insulin resistance, dyslipidaemia in NASH." (PMID 38653921, 2024). "FGF21 knockout should have shown insulin resistance and elevated blood sugar in mice, but the active inflammatory processes also are in demand of high energy consumption, which result in no significant increase of glucose in FGF21 liver." (PMID 38653921, 2024). "Similar to the PDSS2BKO mice, another study found that genetically engineering liver, adipose tissue, or skeletal muscle to secrete FGF21 using adeno-associated virus (AAV), prevented weight gain and insulin resistance associated with aging." (PMID 38212382, 2024). "Firstly, FGF21 reduces insulin resistance by stimulating insulin secretion via the PI3K/Akt signaling pathway, enhancing postprandial insulin sensitivity." (PMID 39687000, 2024). "Combined with GDM mice showing an “FGF21 resistance” phenotype, these results indicate that defects in FGF21 signaling within adipose tissue exacerbate inflammation and insulin resistance in GDM." (PMID 39599611, 2024). "FGF21 is a class of endocrine hepatokines secreted from the liver and adipose tissue and has a crucial role in protecting against insulin resistance." (PMID 38331889, 2024). "miR-99b can bind to the mRNA of FGF21 in liver cells, influencing liver metabolism and exacerbating insulin resistance and glucose tolerance." (PMID 39220365, 2024). "Thiazolidinedione can improve insulin resistance and improve insulin sensitivity in diabetic patients through FGF21." (PMID 38884020, 2024). "In humans, plasma levels of FGF21 are known to be increased with insulin resistance in the liver and muscles." (PMID 37755259, 2023).
Insulin resistance (continued). "We have also examined the potential association between changes in insulin resistance and fasting and postprandial PYY and GLP1 hormones, adiponectin, RBP4, FGF21 and CRP over 3 years of follow-up." (PMID 37055514, 2023). "For instance, the concentration of FGF21 in plasma significantly increases under conditions of type I myotonic dystrophy and insulin resistance." (PMID 38069273, 2023). "Genetic impairment of adipocytes OxPhos function in vivo also protects mice from DIO and insulin resistance, with ablation of FGF21 in this model leading to increased body weight and adiposity, and hepatic steatosis after 8 weeks on high-fat diet (HFD)." (PMID 37818094, 2023). "FGF21 plays many beneficial metabolic roles such as increasing energy expenditure, β-oxidation, adiponectin secretion, and improving insulin resistance." (PMID 36742397, 2023). "It was observed that insulin resistance induced by palmitate in C2C12 cells results in altered muscle secretions (FGF-21, irisin, and myonectin) and glucose transporter 4 (GLUT-4)." (PMID 37298440, 2023). "Although T2D patients had higher baseline FGF21 levels compared with healthy individuals, it appears that hyperinsulinemia or hepatic insulin resistance hampers the exercise-induced secretion of FGF21." (PMID 37755259, 2023). "Surprisingly, FGF21 LKO did not alleviate but even exacerbated whole body glucose metabolic abnormalities in OVX mice, as evidenced by more impaired glucose and pyruvate tolerance, and worsened insulin resistance in OVX+FGF21 LKO mice compared to OVX mice." (PMID 37834368, 2023). "Dietary supplementation with Maqui berry or Mediterranean tomato-based Sofrito sauce enhanced FGF21 signaling in adipose tissue, resulting in improved insulin resistance and increased energy expenditure in HF diet-fed rodents." (PMID 37061742, 2023). "Third, FGF21 can reduce serum insulin and increase insulin sensitivity to protect against systemic insulin resistance." (PMID 36594101, 2023). "The physiological function of FGF-21 is mainly involved in glycolipid metabolism and the metabolic regulation of insulin, body weight reduction and insulin resistance improvement." (PMID 37070097, 2023). "CK-18 values >150 U/l were accompanied by high ALT, GGT and FLI, insulin resistance, postprandial hypertriglyceridemia, elevated FGF-21 and MCP-1 and decreased adiponectin." (PMID 37189422, 2023). "We recently reported that ingesting whey protein isolate suppresses increases in hepatic FGF21 expression and plasma FGF21 levels, which precede hyperinsulinemia, insulin resistance, and hyperglycemia in mice fed a high-fat diet." (PMID 36777350, 2023). "Fibroblast growth factor 21 (FGF21) was also identified amongst the ligand dataset as reversing our insulin resistance fingerprint." (PMID 37494090, 2023). "The hepatokine FGF-21 has been shown to be therapeutically beneficial for the treatment of metabolic diseases via reducing fat mass, hyperglycemia, insulin resistance, dyslipidemia, and non-alcoholic steatohepatitis in rodents and non-human primates." (PMID 37623854, 2023). "Subsequent studies have also demonstrated that circulating FGF21 is closely related to muscle insulin resistance, and FGF21 levels are increased under conditions of hyperinsulinemia or decreased insulin sensitivity in muscle." (PMID 38069273, 2023). "Prostaglandin E1 (PGE1) has also been shown to restore autophagy and insulin resistance in the kidney of type II diabetic (T2DM) rats and promote autophagy-related fibroblast growth factor 21 (FGF21) protein expression, thereby reducing insulin resistance." (PMID 37810881, 2023). "Dimethyl itaconate (DITA) alleviates palmitic-acid-induced insulin resistance in C2C12 myocytes by stimulating AMPK/FGF21/PPARδ signaling." (PMID 38069273, 2023).
Insulin resistance (continued). "Animal studies also suggest that FGF21 is also a critical regulator of circulating adiponectin, a fat-derived hormone that appears to play a crucial role in protecting against insulin resistance and diabetes." (PMID 37869250, 2023). "FGF21 was directly correlated with insulin resistance, although statistical significance was lost after adjustment for body mass index (BMI)." (PMID 36415151, 2022). "FGF21 global knockout mice on a KD had opposite phenotypes, such as body weight gain, insulin resistance, and inflammatory state." (PMID 35572519, 2022). "We have also shown that resistin at the hypothalamic level inhibits insulin signaling as well as that of adiponectin and FGF21, inducing hypothalamic and peripheral insulin resistance." (PMID 36078135, 2022). "The increases in plasma FGF21 and hepatic FGF21 expression precede hyperinsulinemia, insulin resistance, hyperglycemia, and weight gain in mice fed a high-fat diet." (PMID 35163521, 2022). "Overall, the physiological role of FGF21 is to act on white adipose tissue lipolysis, increase insulin-dependent glucose uptake, and revert insulin resistance." (PMID 36140410, 2022). "It is similar to insulin resistance, the patients suffers FGF21 resistance, so it means their body need to secrete more FGF21 for maintain the balance." (PMID 35369322, 2022). "Studies have shown that APS improves glucose and lipid metabolism and improves insulin resistance through the SIRT1-PGC-1α/PPARα-FGF21 signaling pathway." (PMID 35322740, 2022). "RG108 and Azacitidine treatment can relief the DNMT3a-mediated insulin resistance through Fgf21 upregulation." (PMID 35216415, 2022). "Another study showed that Nfe2l2-KO mice developed a phenotype with less insulin-resistance, and Nfe2l2-KO mice had higher plasma levels of fibroblast growth factor 21 (FGF21) and higher FGF21 mRNA levels in liver and WAT compared to WT mice." (PMID 35204118, 2022). "Gut-derived 5-HT can upregulate hepatic FGF21 expression and plasma FGF21 levels, which precede hyperinsulinemia, insulin resistance, impaired glucose tolerance and weight gain in mice fed a high-fat diet." (PMID 35163521, 2022). "A recent report demonstrated that the increases in plasma FGF21 levels and hepatic FGF21 expression precede hyperinsulinemia, insulin resistance, impaired glucose tolerance, and weight gain in mice fed a high-fat diet." (PMID 35163521, 2022). "The researchers demonstrated the potential protection of PGE1 on insulin resistance in renal tubules via autophagy-dependent FGF21 pathway in preventing the progression of DN." (PMID 36091814, 2022). "Hepatic fibroblast growth factor 21 (FGF21), a major factor in regulating hepatic metabolism, glucose, fatty acid and insulin resistance, are increased in patients with NAFLD." (PMID 36447244, 2022). "FGF21 regulates glucose and lipid metabolism in adipose tissue through endocrine pathways, improves insulin sensitivity and insulin resistance, and stimulates glucose uptake in skeletal muscle through GSIS." (PMID 33588950, 2021). "Previous studies have demonstrated that FGF21 and adiponectin are involved in the regulation of insulin sensitivity, and disturbance of the FGF21-adiponectin pathway abrogates FGF21-induced improvement of insulin resistance." (PMID 34321008, 2021). "Expression of endogenous FGF21 is decreased by Dnmt3a-mediated DNA methylation at the Fgf21 promoter, while exogenous FGF21 can restore Dnmt3a overexpression-induced insulin resistance." (PMID 34349728, 2021). "FGF-21 concentrations are increased in metabolic syndrome and are independently related to homeostasis model assessment of insulin resistance (HOMA-IR)." (PMID 33924457, 2021). "Since insulin resistance and hepatic steatosis were less pronounced in females initially, it can be assumed that sex-specific factors (effects of estrogens, adiponectin, FGF21 ) masked the effect of exogenous FGF21." (PMID 34943946, 2021).
Insulin resistance (continued). "It has been shown that DNA methylation at the Fgf21 locus was increased in human DM subjects, which is mediated by Dnmt3a and ultimately lead to insulin resistance." (PMID 34349728, 2021). "Previous studies have shown that FGF21 can improve insulin resistance in peripheral tissues of patients with T2DM, leading to decrease glucose levels independent of insulin." (PMID 34769010, 2021). "In a cross-sectional study, serum FGF-21 level was higher in obese subjects than lean and positively corrected with insulin resistance index homeostasis model assessment." (PMID 33810243, 2021). "In summary, circulating levels of FGF21 are associated with metabolic disturbances in PLWH, including insulin resistance, whereas in uninfected patients, FGF21 levels were mainly related to markers of visceral adiposity." (PMID 34019585, 2021). "Alterations in FGF21 and GDF15 levels were mainly associated with decreased insulin resistance and increased skeletal muscle mass index, respectively." (PMID 33668309, 2021). "In animal models, FGF21 corrects multiple abnormalities of metabolism, including those present in persons with insulin resistance and T2DM." (PMID 34046014, 2021). "Insulin resistance often accompanies with impaired FGF21 signal transduction (also referred as FGF21 resistance) in obese T2DM patients." (PMID 34912302, 2021). "Mice with adipose-specific deletion of Dnmt3a are guarded against diet-induced insulin resistance through upregulated fgf21 expression, indicating that FGF21, as a crucial regulator, is affected by Dnmt3a in adipocytes." (PMID 34968255, 2021). "Studies have found that alprostadil (prostaglandin E1) can reduce the insulin resistance via the autophagy-dependent FGF21 pathway for preventing the progression of diabetic nephropathy." (PMID 34675822, 2021). "Besides this, mice with conditional FGF21 deficiency and FGF21 knock out (KO) showed an impaired glucose metabolism and abnormal body weight, while in FGF21 KO mice a ketogenic diet resulted in severe hepatic insulin resistance compared to that in the wild-type (WT) control." (PMID 33498410, 2021). "Thus, the indirect negative regulation of FGF21 by miR-22 could cause insulin resistance." (PMID 33664851, 2021). "The key findings of this study are three-fold: First, among obese patients with features of the metabolic syndrome, levels of FGF21 were markedly elevated and correlated with markers of chronic low-grade inflammation and insulin resistance." (PMID 33846498, 2021). "In HIV-infected subjects, FGF21 levels showed a strong positive correlation with triglycerides, insulin levels and insulin resistance with a p-value <0.0001." (PMID 34019585, 2021). "The function of FGF21 on metabolism is controversial, as scientists found that Fgf21 knockout prevents high-fat ketogenic diet-induced insulin resistance in mice, but others confirmed the benefits of FGF21 on glucolipid metabolism." (PMID 33363144, 2020). "Improvements in inflammation and insulin resistance seem to be mechanisms involved in the mitigation of atherosclerosis by FGF21 therapy." (PMID 32957703, 2020). "Plasma FGF21 is positively correlated to BMI and insulin resistance in humans which has resulted in discussion of FGF21 resistance." (PMID 33414764, 2020). "After adjusted for age, sex, and preoperative DM status, FGF21 became significantly and positively related to C-peptide (β = 18.887), insulin (β = 2.399), and homeostasis model assessment of insulin resistance index (β = 8.566) after surgery." (PMID 32210348, 2020). "FGF21 treatment alleviated insulin resistance and decreased circulating concentrations of triglycerides, which were significantly correlated with plaque size." (PMID 32957703, 2020). "Chavez A.O., Molina-Carrion M., Abdul-Ghani M.A., Folli F., Defronzo R.A., Tripathy D. Circulating fibroblast growth factor-21 iselevated in impaired glucose tolerance and type 2 diabetes and correlates with muscle and hepatic insulin resistance." (PMID 35087997, 2020).
Insulin resistance (continued). "Correspondingly, FAP knockout mice fed with a high-fat diet improved insulin resistance and glucose tolerance in the liver and adipose tissue, similar to those observed in the FGF21 transgenic mice." (PMID 33277568, 2020). "In support of this approach, an FAP knockout mouse prevented liver steatosis, insulin resistance, glucose tolerance, and increased FGF21 in diet-induced obese mice." (PMID 33277568, 2020). "FGF21 is known to mediate the browning and thermogenesis of adipose tissue, which leads to an improvement of insulin resistance and a reduction of ectopic fat accumulation." (PMID 32698539, 2020). "FGF21 is another critical therapeutic target on the rise that promotes protection from lipid‐induced muscle and liver insulin resistance and T2D." (PMID 33038072, 2020). "Our results, however, demonstrated that whey protein isolate-induced suppression of hepatic FGF21 leads to suppression of insulin resistance and hyperglycemia in mice fed a high-fat diet." (PMID 32978487, 2020). "Elevated FGF21 levels in these diseases are suspected to be signs of FGF21 resistance, similar to the concept of insulin resistance." (PMID 33204460, 2020). "FGF21 is also found to increase insulin sensitivity and endogenous FGF21 is believed to protect obese individuals against insulin resistance." (PMID 32590936, 2020). "The increased level of FGF21 in type II diabetes is due to the compensatory effect induced by insulin resistance in these patients." (PMID 32095207, 2020). "The FGF21 levels increased in type 2 diabetes and is positively correlated with hypertension, hyperglycemia, glycated hemoglobin level, insulin resistance, and hsCRP level." (PMID 30927227, 2019). "The therapies of insulin resistance can be classified based on their intended targets, including bile acid-based insulin sensitization, peroxisome proliferator-activator receptors, FGF21, and metformin." (PMID 30642126, 2019). "FGF21 metabolic benefits range from reducing body weight to alleviating hyperglycemia, insulin resistance, and improvement of lipid profiles." (PMID 31374856, 2019). "We found that FGF21 reduced hyperglycemia and ameliorated insulin resistance in type 2 diabetic mice, an effect that was totally lost in type 1 diabetic mice." (PMID 31511499, 2019). "They found that Dnmt3a mediates insulin resistance by methylating the Fgf21 promoter; FGF21 hypermethylation was evident in human subjects with T2D and correlated negatively with FGF21 expression in human adipose tissue." (PMID 31896238, 2019). "It is known that FGF21 exerts multiple metabolic effects, including attenuation of body weight gain and insulin resistance." (PMID 31394746, 2019). "Data from a recent study have shown that JNK in the liver tissue of mouse plays a critical role in insulin resistance via suppression of PPAR-controlled FGF21 pathway." (PMID 31270248, 2019). "Energy restriction consistently reduced liver fat content in a linear fashion, but induced pronounced and opposite alterations in fasting insulin and FGF-21 already after 3 days, suggesting rapid improvement of insulin resistance." (PMID 31685793, 2019). "Activation of AhR protects against fatty liver induced by insulin resistance by activating fibroblast growth factor 21 (FGF21) to regulate lipid and energy metabolism in such mice." (PMID 31638212, 2019). "In the present study, we found that FGF21 improves hyperglycemia, insulin resistance and endothelium-dependent relaxation of aorta in two T2D mouse models (HFD-STZ-induced and db/db)." (PMID 31511499, 2019). "The administration of FGF21 directly into the cerebrospinal fluid increases energy expenditure and reduces insulin resistance in obese rats." (PMID 30927227, 2019). "One year after adrenalectomy, we find an improvement in glucose metabolism and insulin resistance, followed by a decrease in FGF21, despite an increase in body weight due to the disappearance of the hypermetabolic effect of catecholamines." (PMID 30959789, 2019).